HIF1A (hypoxia inducible factor 1 subunit alpha)
Diseases named in the same sentence as HIF1A in open-access papers (continued):
Sharing a sentence is not in itself a finding about the gene and the disease.
tumor (continued). "Evodiamine, a natural anti‐tumour compound, inhibits the lactylation modification of hypoxia inducible factor 1 subunit alpha (HIF1a) by suppressing intracellular lactate production, thereby weakening HIF1a's inhibitory function on Sema3A." (PMID 39456119, 2024). "To specifically test the role of HIF-1α in restraining NK cell functions within the tumor, we generated Ncr1cre x Hif1af/f x Kaede mice and grafted these, alongside cre-negative littermate controls with MC38 tumors." (PMID 38267402, 2024). "The increased perfusion vasculature further ameliorated hypoxia in the tumor region, as evidenced by immunofluorescence of the classical hypoxia marker, HIF‐1α." (PMID 38884220, 2024). "It has been indicated that the HIF-1α-mediated PKC/c-Src/HIF-1α signaling pathway is activated by Cmurc chemokine ligand 5/C-C chemokine receptor 5, leading to an increase in tumor angiogenesis dependent on VEGF in the OS microenvironment." (PMID 38327979, 2024). "Under hypoxia conditions, the hypoxia‐inducible factor (HIF)‐1α pathway is activated in tumor cells, which during oxygen stress, plays a role as an adaptive mechanism." (PMID 37994401, 2024). "HIF-1α is mainly expressed in TAMs, and TAM-derived HIF-1α is closely correlated with worse tumor stage and development, and independently related to poor OS and outcomes in RCC patients." (PMID 39169402, 2024). "In particular, the overexpression of HIF-1α in glucose augments glucose absorption in tumor cells through the elevation of glucose transporter levels." (PMID 38799423, 2024). "Surprisingly, HIF1α have a low expression and function as a tumor suppressor in renal cell carcinoma." (PMID 38263248, 2024). "This includes the accumulation of metabolites like succinate and fumarate, which further stabilize HIF-1α and promote a metabolic state conducive to tumor growth." (PMID 39408832, 2024). "It is established that HIF-1α mRNA is highly expressed in cancers and that HIF-1α mRNA overexpression supports cancer progression through various mechanisms, including tumor cells proliferation, invasive, metastasis, as well as angiogenesis." (PMID 39691597, 2024). "The hydroxylated prolyl sites are recognized by the Von Hippel–Lindau (VHL) tumor suppressor, which induces degradation of HIF-1α by the ubiquitin–proteasome system (UPS)." (PMID 39361163, 2024). "In tumor cells, the result of HIF-1α activation in hypoxia is to shift energy production by increasing glycolysis and decreasing mitochondrial function." (PMID 39475618, 2024). "Therapies that inhibit HIF1α directly or modulate its associated regulatory mechanisms, such as the SMURF2 pathway, have the potential to impair tumor angiogenesis, reduce immune suppression, and reprogram tumor metabolism." (PMID 39697237, 2024). "The activation of HIF-1α was one of the main initiating factors of the interaction between macrophage and tumor cells." (PMID 38880903, 2024). "This hypoxic state is a critical factor in tumor progression and is known to activate hypoxia-inducible factor 1-alpha (HIF-1α)." (PMID 38473413, 2024). "Additional mutations impacting genes like HIF1A, IDH1, or tumor suppressors further introduce variability in metabolic wiring between CRC tumor cells and microenvironments." (PMID 39273409, 2024). "For example, HMGB1 can regulate the YAP-mediated HIF-1α pathway and activate the transcription of glycolysis-related genes, which in turn induces glycolysis and promotes the malignant progression of tumor." (PMID 39816354, 2024). "Conversely, the overexpression of Pfn1 restores SIRT3 levels, resulting in the destabilization of HIF-1α and subsequent suppression of tumor growth." (PMID 39682281, 2024).
tumor (continued). "HIF-1α and HIF-2α are the main mediators of acute and chronic hypoxia, respectively, and have been reportedly associated with increased tumor aggressiveness and progression." (PMID 39361163, 2024). "They argued that a loss of HIF-1α in CD8+ T cells leads to decreased tumor infiltration and tumor cell death and altered tumor angiogenesis." (PMID 39202223, 2024). "Simultaneously, we identified a pronounced expression of the TF HIF1A, known to facilitate tumor immune escape within SPP1+ M1 macrophages, a population that was notably abundant in the NpCR group." (PMID 39170612, 2024). "Hypoxia microenvironment ubiquitously exists in a variety of solid tumors, including HNSCC, because of the rapid tumor growth and inefficient blood supply, leading to the increasing stabilization of hypoxia-inducible factor 1α (HIF1α)." (PMID 38485986, 2024). "Owing to the enhanced accumulation in tumor tissue, the protein expression of HIF-1α in tumor cells pretreated with KPF NPs is lowest among all therapeutic groups." (PMID 39339168, 2024). "The results showed that the density of TLS invading the front edge and internal tumor area was significantly reduced, and was related to the high tumor budding and the increased expression of HIF1α and LDH5." (PMID 38583352, 2024). "Hif-1α plays a crucial role in the hypoxic response of tumor cells, controlling the upregulation of vital factors like VEGF, necessary for solid tumor expansion." (PMID 38584671, 2024). "Tumor oxygenation: the green fluorescence of HIF-1α almost disappeared after treat with PFC-PLGA-IR780 combined PDT and PTT." (PMID 39728157, 2024). "It has been found that in tumor cells HIF1α can help tumor cells survive in a hypoxic environment by influencing cellular metabolism, promoting invasive dissemination, modulating pH, and impacting inflammation." (PMID 38315272, 2024). "Immunohistochemical staining was used to assess Ki67, NF-κB, and HIF-1α expression P versus F3 generation tumor tissues." (PMID 39525113, 2024). "Several studies have confirmed that both HIF-1α and VEGF are strongly expressed in GBM, and both present a remarkably similar distribution around areas of necrosis that correlate with tumor grade and are associated with poor prognosis." (PMID 39055895, 2024). "In the HIF1A-dependent pathway, MCT1 transports lactate into endothelial cells to inactivate PHDs and stabilize HIF1A that then induces expression of vascular endothelial growth factor (VEGF) to promote angiogenesis in tumor cells under normoxic conditions." (PMID 39529665, 2024). "Elevated level of HIF1α facilitates the metabolic adaptation of hypoxic tumor cells by increasing utilization and uptake of glucose, or redirecting the glucose metabolism from oxidative phosphorylation to glycolysis." (PMID 38715141, 2024). "The preliminary findings of our study indicate that the immune response exerts a certain influence on tumor metabolism, and HIF-1α plays a crucial role as a regulatory factor in this process." (PMID 38448544, 2024). "Accordingly, this has spurred the exploration of changes in ALDH-1, SOX2, and HIF-1α in tumor tissues." (PMID 38962320, 2024). "The upregulation of STAT3, a transcription factor known for its role in cell survival and immune evasion, along with HIF1A facilitates a cellular environment conducive to tumor growth and immune system suppression." (PMID 39468431, 2024). "2-Methoxyestradiol (2ME2) inhibits HIF1α, inhibits tumor growth, and is being tested in phase I and II in various cancers, including GBM, with promising efficacy and low toxicity." (PMID 38893207, 2024). "HIF-1α not only regulates the expression of cancer-related genes in TAMs but also induces metabolic changes, driving tumor development even under conditions of nutrient deprivation and hypoxia." (PMID 38602536, 2024).
tumor (continued). "Further studies found that heme oxygenase-1 (HO-1), triggered by HIF-1α, scavenges intracellular ROS from SP and inhibits the differentiation of tumor cells, leaving patients with a poor prognostic outcome." (PMID 37588219, 2024). "As is well known, hypoxia can effectively activate HIF-1α signaling, which influences multiple steps during tumor metastasis." (PMID 38280861, 2024). "Under hypoxic conditions, tumor cells stabilize hypoxia-inducible factors (HIFs), primarily HIF-1α, which promotes angiogenesis, the formation of new blood vessels from pre-existing vasculature, to re-establish oxygen supply." (PMID 39529126, 2024). "In vitro analyses revealed that the knockout of GLUT-1 and/or HIF-1α reduces tumor growth and radio resistance." (PMID 38474362, 2024). "MIF drives tumor metabolic re-programming to confer survival in hypoxic environments by inducing anaerobic metabolism via the NF-κB and HIF-1α pathways." (PMID 38732068, 2024). "HIF-1α and pimonidazole serve as pivotal markers for tumor hypoxia, delineating acute and chronic hypoxic conditions, respectively." (PMID 39621211, 2024). "Increasing evidence has shown that HIF-1α promotes tumor progression, metastasis, and therapeutic drug resistance by maintaining cancer stemness." (PMID 39728923, 2024). "In tumor cells like 4T1, quercetin reduced intra-tumoral HIF-1α in a hypoxia-dependent manner, while in healthy cells, it increased HIF-1α accumulation." (PMID 39519572, 2024). "USP7 inhibition affects HIF‐1α transcriptional modulation, tumor hypoxia and remodeling of the tumor microenvironment creating a permissive immune micro‐climate for infiltrating lymphocytes turning immunologically ‘cold’ tumors, ‘hot’." (PMID 38602256, 2024). "In rapidly growing tumor tissues, hypoxia-inducible factor-1α (HIF-1α) performs an essential function in the metabolic reprogramming of tumor cells through the stimulation of gene transcription that encodes glycolytic enzymes and glucose transporters." (PMID 39346921, 2024). "Collectively, we show that HIF1α, by maintaining glycolysis and [acetyl-CoA], controls effector function and tumor-killing ability of hypoxic T cells." (PMID 39477954, 2024). "Given its importance, HIF1α is regarded as a master oncogene in tumor progression, and thus its regulatory mechanisms merit further investigation." (PMID 38485986, 2024). "To determine the DNA methylation status of EGLN1-3 and HIF1A promoter regions in both tumor and normal tissues in our patient cohort (n = 77), we used methylation-sensitive High-Resolution Melting Analysis (MS-HRM)." (PMID 38928200, 2024). "Recent studies have shown that HIF1α, as a transcription factor that can be activated by hypoxic environments, plays an important role in tumor metabolism." (PMID 38195606, 2024). "FUNDC1 was predominantly located in the cytoplasm of tumor cells, and HIF-1α was detected in the cytoplasm and nucleus." (PMID 39668821, 2024). "p-AKT enhances the expression of the main stemness-regulating transcription factors (NANOG, OCT-4, and SOX2), anti-apoptotic proteins, and HIF1A-mediated hypoxia, promoting self-renewal, tumor progression, chemoresistance and radioresistance." (PMID 38720782, 2024). "HIF1A is a transcription factor that responds to low oxygen levels in the tumor microenvironment, a common characteristic of solid tumors." (PMID 39458948, 2024). "Studies in the past have showcased HIF-1a’s ability to positively regulate PD-L1 under hypoxic conditions, as well as HPV16 E6’s upregulation of HIF-1a in the tumor microenvironment." (PMID 38257813, 2024). "HIF-1α is a key protein in the hypoxic microenvironment that reshapes tumor metabolism and induces angiogenesis and vascular mimicry during the progression of multiple cancers." (PMID 38720298, 2024). "Elevated HIF1A expression in cancer frequently correlates with tumour hypoxia, exerting profound influences on tumour progression, metastasis, and resistance to therapeutic response." (PMID 39001444, 2024).
tumor (continued). "In fact, investigation of primary luminal A tumour heterogeneity suggests the expression of the ERα is negatively correlated with the expression of HIF-1α within a cycling hypoxia microenvironment." (PMID 39282472, 2024). "HIF1α appears to play a pivotal role in EMT dynamics by promoting mesenchymal gene expression in luminal as well as in mesenchymal clusters at the primary tumour, thereby generating hybrid E/M and extra-M subpopulations." (PMID 38238426, 2024). "This includes the accumulation of mitochondrial ROS, oncometabolites, and the activation of HIF-1α, all of which play a crucial role in tumor growth regulation." (PMID 38880883, 2024). "In solid tumors, the TME is always characterized by hypoxia, leading to the upregulation of HIF‐1α in tumor cells." (PMID 39184861, 2024). "In in vitro and in vivo studies, it has been identified that PML-RARα boosts pro-leukemic functions driven by HIF-1α, including cell migration, BM neo-angiogenesis, and self-renewal of tumor cells." (PMID 37588219, 2024). "PX-12 has exhibited potent inhibition of HIF-1α accumulation and downstream gene expression across various tumor models, accompanied by a significant reduction in angiogenesis." (PMID 39575238, 2024). "Given the central role of HIF1α in tumor adaptation to hypoxia, targeting this pathway offers a strategic approach to disrupt essential processes in tumor progression." (PMID 39697237, 2024). "In the treatment of LC, CHE can reduce tumor growth in Lewis lung cancer transplanted mice by targeting the NF-κB/HIF-1α signaling pathway and down-regulating the expression levels of NF-κB and HIF-1α proteins, thereby achieving a therapeutic effect." (PMID 39239653, 2024). "Direct measurements of tumor tissue oxygen partial pressure and HIF-1α immunohistochemical staining revealed an increase in oxygen partial pressure and a reduction in tumor hypoxia following treatment at these parameters." (PMID 39872052, 2024). "In HNSCC patients with hypermethylation of HIF1A in normal tissue, we noted a reduction in HIF1A mRNA levels compared to tumor tissue (p = 0.04)." (PMID 38928200, 2024). "Another recent study found that HIF-1α prevents tumor cells from being subjected to immune surveillance with enhanced levels of carbonic anhydrase IX (CA9) expression." (PMID 37588219, 2024). "This bidirectional regulation is of high importance in the regulation of tumor progression, considering that HIF-1α is involved in tumor angiogenesis through a variety of mechanisms including a regulatory mechanism of miRNAs." (PMID 39055895, 2024). "Of note, suppression of metastasis and EMT hybrid states by echinomycin in PyMT1/GPx2KD tumours was recapitulated by GPx2 OE or induction in PyMT2 tumours, thus reiterating a strong connection between GPx2 KD, HIF1α, partial EMT, and metastasis." (PMID 38238426, 2024). "Specifically, HIF-1α modulates glucose metabolism, angiogenesis, and tumor proliferation in hypoxic environments." (PMID 38700744, 2024). "The HDAC1 can improve HIF-1α activity, which can promote aerobic glycolysis in tumor cells by inhibiting acetylation or degradation of HIF-1α." (PMID 39876842, 2024). "It is well known that PX-478 and EZN-2968 are dose-dependent drugs that reduce the secretion of HIF-1α and VEGF and cause tumor shrinkage in xenograft animal models, and that satisfactory results were obtained in phase I clinical trials." (PMID 37588219, 2024). "Studies have shown that high levels of HIF-1α and HK-II promote glycolysis in tumor cells under hypoxic conditions, thereby increasing drug resistance." (PMID 39611141, 2024). "Specifically, SMURF2’s activity facilitates the maintenance of low intracellular HIF1α levels, impacting cellular responses to hypoxia and inhibiting tumor growth and metastasis." (PMID 39697237, 2024). "DHA, ION-31a, and Genistein effectively downregulate VEGF expression in tumor cells by suppressing the HIF-1α pathway, thereby inhibiting BC proliferation and metastasis." (PMID 39434182, 2024).
tumor (continued). "In patients with ccRCC, the presence of HAF can significantly enhance tumor progression through ubiquitination and degradation of HIF-1α." (PMID 39748950, 2024). "NF-κB plays a crucial role in tumor proliferation and resistance development, and has been reported to regulate the transcriptional expression of HIF-1α and YY1 transcription factors." (PMID 39063014, 2024). "In head and neck squamous carcinoma, the HIF-1α–MIF axis contributed to the recruitment of myeloid (CD11b + -Gr-1 +) cells to enhance tumor growth and angiogenesis." (PMID 38685050, 2024). "Through co‐culture experiments, we observed that MIF was regulated by the TF HIF‐1α, which can promote tumour progression." (PMID 39113235, 2024). "Tumor growth often outperforms blood supply, leading to an increase in HIF-1α expression within hypoxic regions." (PMID 38339408, 2024). "HIF-1α, an oxygen-dependent transcription factor, is highly expressed in tumor cells under hypoxic conditions, contributing significantly to tumorigenesis, development, invasion, metastasis, and apoptosis." (PMID 38611849, 2024). "Recent reports have demonstrated that HIF-1α overexpression in TAMs promotes tumor progression and enhances drug resistance." (PMID 38602536, 2024). "Recent research found that downregulation of HIF-1a can lead to a decrease in tumor glycolytic metabolism related pathways." (PMID 39091919, 2024). "Compared to WT mice (n = 27), similar tumor volume and tumor weight were observed in HIF1α MKO mice (n = 14)." (PMID 38422022, 2024). "HIF-1α regulates crucial processes, such as drug resistance, cell proliferation, evasion of tumor growth suppression, apoptosis, unlimited replication, induction of angiogenesis, invasiveness, and metastasis." (PMID 38766303, 2024). "The expression of HIF1α in tumor tissue was remarkably higher when compared to their corresponding surrounding tissues which was noticed in SULT1E1 expression." (PMID 39132498, 2024). "In particular, periprostatic adipose tissue has been found to induce tumor switch towards the Warburg phenotype through Akt/HIF-1α activation." (PMID 38904014, 2024). "The increased accumulations of succinate and mtROS inactivate PHD, consequently upregulating HIF-1α, which significantly contributes to tumor growth promotion in PDLIM2-knockdown conditions." (PMID 38880883, 2024). "In this context, evidence suggests that NRF2 silencing blocks HIF-1α signaling to suppress blood vessel formation and xenograft tumor growth." (PMID 38424190, 2024). "Collectively, these data indicate that PRMT5 enhances the expression of genes involved in tumor progression via HIF-1α pathway activation." (PMID 38666828, 2024). "HIF1α responds acutely to hypoxia, while HIF2α regulates tumor cell response to chronic hypoxia, making it a potential therapeutic target." (PMID 38893207, 2024). "Given its pivotal role in tumor progression and metastasis, HIF1A represents a promising therapeutic target." (PMID 39458948, 2024). "In models of a VX2 liver xenograft tumor, the combination of rapamycin with TACE has also been demonstrated to exhibit anti-tumor neovascularization activity and to inhibit the expression levels of iNOS, HIF-1α, VEGF, Bcl-2, and Bax." (PMID 39204162, 2024). "The hypoxia marker, nuclear HIF1α, can be expressed both by tumor cells and immune cells in the TME and our analysis identifies both populations." (PMID 38805346, 2024). "The interaction of 40 with HIF-1α, a key regulator of tumor adaptation to hypoxic conditions, suggests that it inhibits cancer cell survival by targeting the HIF-1α pathway, making it a promising candidate for selective anticancer therapy." (PMID 39407697, 2024). "HIF-1α is specifically increased in the oxygen-deprived tumor microenvironment, stimulating the activation of genes that are crucial for the development of blood vessel structures." (PMID 39272834, 2024).